HSP90B1 (heat shock protein 90 beta family member 1)
Diseases named in the same sentence as HSP90B1 in open-access papers (continued):
Sharing a sentence is not in itself a finding about the gene and the disease.
tumor (continued). "As expected, the results showed that B lymphocytes (tumor fraction) from VAR-CLLs showed a higher level of HSP90B1 expression than B lymphocytes from WT-CLLs (P = 0.001), and also from the normal cells from the same patients (VAR-CLLs) (P < 0.001)." (PMID 25880332, 2015). "The expressions of HSP90B1, USP34 and HMGN2 were significantly negatively associated with tumour grade (p<0.001)." (PMID 22363530, 2012). "This hormonal treatment effect cannot be explained by hormone receptor status bias because OS was significantly better for patients with low vs. high tumour expression of HSP90B1 for all molecular subtypes." (PMID 22363530, 2012). "These analyses identified decorin (DCN) and endoplasmin (HSP90B1) which play important roles regulating the tumour microenvironment and in pathways related to tumorigenesis." (PMID 22363530, 2012). "An important and novel finding is that in terms of OS, patients with high expression of HSP90B1 in tumour cells appear to benefit significantly from hormonal treatment (HR: 1.07 vs. 2.8 for no hormone treatment group)." (PMID 22363530, 2012). "Notably, heightened HSP90B1 expression correlated with advanced clinical T Stage, the presence of distant metastasis, and higher tumor grade." (PMID 38590708, 2024). "HSP90B1 has pro-cancer effects and is closely related to tumor development and immunity invasion, and therefore, may become a new biomarker of cancer diagnosis, prognosis and a novel target for future cancer therapy." (PMID 38243263, 2024). "The expression of HSP90B1 was markedly higher in tumor cells than in immune cells (p < 0.05)." (PMID 38243263, 2024). "Targeting HSP90B1 has been explored as a potential strategy for tumor suppression." (PMID 39149033, 2024). "First, tumor cells may reduce drug sensitivity by altering the structure or expression of HSP90B1, the primary target of FKC." (PMID 38711062, 2024). "Furthermore, we investigated the correlation of HSP90B1 expression in 33 tumors with infiltrating immune cells within the tumor microenvironment." (PMID 38243263, 2024). "In addition, FKC can affect NPC tumor growth and metastasis in vivo by regulating the HSP90B1/EGFR pathway." (PMID 38711062, 2024). "Furthermore, the angiogenic potential of NPC, influenced by HSP90B1 expression, was explored using endothelial cell migration and tube formation assays under various tumor-conditioned media." (PMID 38711062, 2024). "More importantly, HSP90B1 promoted the localization of glucose transporter type 1, a key rate-limiting factor of glycolysis, on the plasma membrane, which in turn enhanced glycolytic activity and subsequently tumor growth and radioresistance of GBM cells." (PMID 37750323, 2023). "In BRCA and PRAD, HSP90B1 expression was negatively correlated with tumour-associated fibroblast infiltration, while in HNSC and THYM, HSP90B1 expression was positively correlated with tumour-associated fibroblast infiltration." (PMID 36291587, 2022). "Thus, owing to its ability to activate anti-tumour immune responses on its own, extra-cellular HSP90B1 has potential as an antigen in tumour vaccines." (PMID 36291587, 2022). "Additionally, immunohistochemical staining of the Human Protein Atlas database showed that HSP90B1 was highly expressed in most malignant tumours." (PMID 36291587, 2022). "DFS analysis indicated that the high expression of HSP90B1 was associated with poor prognosis of ACC (p = 0.0022), BLCA (p = 0.041), CHOL (p = 0.021), KIRC (p = 0.02), KIRP (p = 0.0054), LUAD (p = 0.038), LUSC (p = 0.047), and UVM (p = 0.024) tumours." (PMID 36291587, 2022). "Despite the increasing number of research devoted to the investigation of the role of HSP90B1 in many disorders, including cancer, it remains unclear whether HSP90B1 plays a pro-oncogenic or anti-oncogenic role in tumour pathogenesis." (PMID 36291587, 2022). "The TCGA database was used to examine the genetic changes of HSP90B1 in various tumour samples." (PMID 36291587, 2022).
tumor (continued). "This study identified four novel phosphorylation sites, which could be one of the important pathways through which HSP90B1 functions in tumours." (PMID 36291587, 2022). "In this study, HSP90B1 was highly expressed in the majority of tumours." (PMID 36291587, 2022). "The N-terminus and C-terminus of HSPA9 interact with HSP90B1 to regulate tumor cell functions." (PMID 34712697, 2021). "HSP90b1 plays an important role in tumour cell growth and promotes protein refolding." (PMID 28821885, 2017). "HSP90B1 is a heat shock chaperone protein that stabilizes and refolds denatured proteins after stress, facilitating cell survival during conditions commonly seen in the tumour microenvironment." (PMID 22363530, 2012). "Kaplan-Meier analysis (median follow-up of 12.8 years, range: 1.1 to 23.5 years) showed that patients whose tumours express high levels of DCN or HSP90B1 in the malignant epithelium have significantly lower OS and DFS compared to patients with lower expression of either marker." (PMID 22363530, 2012). "Therefore, targeting HSP90B1 may be more lethal to tumor cells, which provides a strategic therapeutic window." (PMID 38243263, 2024). "Furthermore, GO and KEGG analyses suggest that HSP90B1 could regulate the occurrence and development of tumours via various mechanisms, such as participating in ER stress response or regulating apoptosis." (PMID 36291587, 2022). "Notably, an emphasis on the function of HSP90B1 in tumour development is currently observed." (PMID 36291587, 2022). "However, the examination of HSP90B1 has been limited to a select few forms of cancer, and its significance in other types of tumours remains unknown." (PMID 36291587, 2022). "Furthermore, KEGG data showed that “thyroid hormone synthesis” and “protein processing in endoplasmic reticulum” could be involved in the effect of HSP90B1 on tumour pathogenesis." (PMID 36291587, 2022). "HSP90B1, a member of the HSP90 family, is abundant in cancer cells and can act as a carrier of tumor antigenic peptides, playing a critical role in tumor antigen presentation and activation of CD8+ T lymphocytes." (PMID 39149033, 2024). "In the next place, we explored the HSP90B1 expression of infiltrating immune cells within the tumor microenvironment in KIRC and conducted a comparative analysis of HSP90B1 expression across the identified cell types." (PMID 38243263, 2024). "Heat-shock proteins (HSPs) —also phosphorylating AKT—were upregulated in CLs and normal-like TN tumours; some of them—HSP90AA1 and HSP90B1—were also upregulated in basal-like TN tumours, and one—HSP90B1— was upregulated across all sample groups." (PMID 36220861, 2022). "The corresponding heat map further proved that HSP90B1 was positively correlated with the six genes (HSPA5, PDIA3, MANF, PDIA4, CALR, and PDIA6) in various tumours." (PMID 36291587, 2022). "Therefore, tumours with high HSP90B1 expression are speculated to have a bad prognosis." (PMID 36291587, 2022). "mRNA Log2 expression comparisons between non-tumor control and GBM specimen, respectively, were as follows: HSPA5, 10.38 ± 0.01 vs. 11.56 ± 0.02, p < 0.001; HSP90B1, 8.36 ± 0.08 vs. 8.98 ± 0.02, p < 0.001." (PMID 30709011, 2019). "We found HSP70, HSP90B1 (GP96), HSP90 and HSPD1 (HSP60) protein expression in both primary tumours and cell lines." (PMID 29702669, 2018). "The band intensity observed in the western blots suggested that levels of HSP90B1 and HSP60 protein expression are higher in cell lines than primary tumours, which correlates with the levels of expression detected at the mRNA level for these two genes." (PMID 29702669, 2018). "In comparison, HSP90B1 (GP96), HSP90AB1 and HSPD1 (HSP60) were expressed at significantly higher levels in tumour cell lines than skin." (PMID 29702669, 2018).
tumor (continued). "isolated tumor rejection antigens from the membrane and cytosol fractions of Meth A and CMS5 which was later recognized as ER HSP90 homolog, glucose-regulated protein 94 (GRP94/HSP90B1/gp96/ERp99/Endoplasmin)." (PMID 39148727, 2024). "Through a comprehensive analysis of Tumor ImmuneScore, StromalScore, and ESTIMATEScore, we observed a negative correlation between HSP90B1 expression and tumor purity in BLCA, KIRC, and PCPG (all p < 0.05)." (PMID 38243263, 2024). "It was found that FKC treatment suppressed tumor volume and weight and inhibited glycolysis and angiogenesis-related protein expression and phosphorylation of the EGFR/PI3K/Akt/mTOR pathway, whereas knockdown of HSP90B1 strengthened the effect of FKC." (PMID 38711062, 2024). "In the current study, we revealed that HSP90B1 played an important role in developing radioresistance by promoting membrane localization of GLUT1 and subsequently leading to an activated glycolysis in GBM tumor cells." (PMID 37750323, 2023). "BD treatment may induce ANXA2, TGFI, FN1, HSP90B1 down-regulation, and FRK up-regulation to inhibit tumor metastasis by regulating autophagy, hypoxia, β-catenin, and STAT3 signaling pathways." (PMID 34685653, 2021). "The results showed that the expression of HSP90AA1, HSP90AB1, and TRAP1 was positively correlated to the tumor purity, while that of HSP90B1 was not." (PMID 33145341, 2020). "HSP90B1 and HSPD1 were also expressed at higher levels in cell lines than primary tumours." (PMID 29702669, 2018). "Mean TMA protein expression levels of HSP90B1 and DCN showed the strongest statistical association with presence of LN metastasis being significantly higher in LN positive tumours relative to LN negative tumours (HSP90B1 p = 0.049; DCN p<0.001)." (PMID 22363530, 2012). "Taken together, these findings establish HSP90, and particularly HSP90B1, as a prognostic biomarker and a functional DAMP in ccRCC, whose targeting may not only disrupt tumor cell homeostasis but also reprogram the tumor immune microenvironment toward enhanced immunogenicity." (PMID 41009692, 2025). "Therefore, genes VEGFA, ANXA1, HSP90B1, PSMA7, PRDX6, and PPP1CB may be new targets for anti-tumor effects in the future." (PMID 36741702, 2022). "In view of BC-related function of these BLBC-specifically secreted proteins, several factors involved in tumor progression and metastasis showed increased secretion, including CD44, heat shock protein family A member 5 (HSPA5), and heat shock protein 90 beta family member 1 (HSP90B1)." (PMID 31146747, 2019). "However, no changes in HSP90B1 mRNA expression were observed between tumor and normal fractions in CLLs without the SNP (P = 0.201)." (PMID 25880332, 2015).
cancer (157 papers, 2003 to 2026). A tumor composed of atypical neoplastic, often pleomorphic cells that invade other tissues. "Studies suggest that hsp90b1 is highly expressed in various cancers, with its overexpression often associated with poor prognosis." (PMID 41155202, 2025). "Patients with high expression of HSP90B1 in cancer cells are more susceptible to worse prognosis in comparison to those with low level of expression." (PMID 38243263, 2024). "Our findings, which are consistent with previous research, indicated that RAB32, SMYD3, AP2M1, and HSP90B1 were associated with cancer progression." (PMID 35610596, 2022). "Our comprehensive pan-cancer analysis of HSP90B1 revealed that the high expression of HSP90B1 was associated with the poor clinical prognosis of various human cancers, indicating that HSP90B1 can be used as an effective biomarker in cancer." (PMID 36291587, 2022). "For example, HSP90B1 was positively associated with 9 cancer hallmarks, such as proliferation, EMT, and inflammation, which is consistent with the findings of other studies." (PMID 33225964, 2020). "HSP90B1, a conserved member of the heat shock protein family, growing evidences have demonstrated that it might be closely associated with cancer development." (PMID 38243263, 2024). "Additionally, the mutation burden of HSP90B1 in cancer was evaluated along with the survival rate of patients with cancer patients." (PMID 36291587, 2022). "Notably, high levels of HSP90B1 are associated with poor prognosis in a variety of cancers." (PMID 38711062, 2024). "Hsp90b1 expression is correlated with poor prognosis, advanced stages, and immunosuppression in different types of cancer, including RCC." (PMID 40538439, 2025). "HSP90B1, the human ortholog of Gp93, has emerged as a significant contributor to cancer development." (PMID 39965405, 2025). "CCDC134, STT3A and OSTC showed a strong signature of genetic co-essentiality with each other and the LRP6 chaperone HSP90B1 in the Cancer Dependency Map (DepMap)." (PMID 39509507, 2024). "High expression of HSP90B1 is associated with poor prognosis and is closely related to PD1, indicating its potential as a prognostic biomarker and therapeutic target for cancer immunotherapy." (PMID 39691874, 2024). "Pan-cancer analysis, along with data from the GEO, TCGA, and GTEx databases, indicated that HSP90B1 is highly expressed in ccRCC tissues." (PMID 39149033, 2024). "Taken together, HSP90B1 emerges as a promising avenue for breakthroughs in cancer diagnosis, prognosis and therapy." (PMID 38243263, 2024). "To investigate the relationship between HSP90B1 and various cancers, we assessed differences in HSP90B1 expression across different cancer and normal tissues." (PMID 38243263, 2024). "Recent studies have observed that high expression of HSP90B1 has prognostic significance in some malignant tumors." (PMID 38711062, 2024). "This phenomenon has been confirmed by elevated expression levels of HSP90B1 observed in various cancer tissues." (PMID 38665430, 2024). "Our previous studies have shown that FKC is a natural inhibitor of HSP90B1, which can effectively reduce HSP90B1 expression in cancer cells." (PMID 38711062, 2024). "HSP90B1 interacts with over 100 different client proteins, underscoring its substantial role in cancer biology." (PMID 38590708, 2024). "Our research probes the mechanistic role of HSP90B1 in regulating the PI3K/Akt/mTOR pathway, a key downstream effector of EGFR signaling implicated in the oncogenesis of various cancers." (PMID 38711062, 2024). "A pan-cancer analysis was conducted to explore the expression levels of HSP90B1 across various cancer types." (PMID 39149033, 2024). "Previous studies have demonstrated that FKC is a natural inhibitor of HSP90B1, which can effectively reduce the expression of HSP90B1 in cancer cells." (PMID 38711062, 2024). "Recently, HSP90B1 targeted therapies have been developed in cancer treatment including small molecular compounds." (PMID 38243263, 2024).
cancer (continued). "Immunohistochemistry (IHC) assays further verified the upregulation of HSP90B1 in cancer tissues versus normal tissues." (PMID 38590708, 2024). "HSP90B1 plays a pivotal role in regulating cancer cell survival and death by maintaining ER stress sensors, protein folding capacity, and inhibiting pro-apoptotic mechanisms (Kim, Cho & Lee, 2021)." (PMID 38590708, 2024). "For the first time, to the best of our knowledge, this study aims to comprehensively analyse the role of HSP90B1 in various cancers." (PMID 36291587, 2022). "Based on these findings, HSP90B1 has potential as a biomarker for determining the outlook for patients with cancer." (PMID 36291587, 2022). "Previous studies have shown that HSP90B1 maintains a delicate balance between cancer cell survival and death by regulating endoplasmic reticulum (ER)-related pro-apoptotic mechanisms." (PMID 36741702, 2022). "HSP90B1 regulates the balance between cancer cell survival and death by maintaining ER protein folding capacity, ER stress sensors, and suppressing ER-associated pro-apoptotic machinery." (PMID 36186448, 2022). "The TIMER method was used to evaluate the expression patterns of HSP90B1 in various cancer types, which were obtained from the TCGA database." (PMID 36291587, 2022). "Using the TCGA database, the current study’s all-encompassing method comprised an investigation of the HSP90B1 expression level in 33 different cancers." (PMID 36291587, 2022). "Networks of HSP70 or HSP90 (including HSPA8, HSPA5, and HSP90B1) play important roles in the regulation of energy metabolism as well as in cancer cells’ oncogenesis and malignant progression." (PMID 36038612, 2022). "Collectively, these studies suggest that cell surface HSP90B1 has potential as a therapeutic target for cancer treatment." (PMID 36291587, 2022). "Data from the TCGA and GTEx databases were used to analyse the expression of HSP90B1 in different cancer and normal tissue types." (PMID 36291587, 2022). "Similar to the pro-oncogenic role of Hsp90AA1, Hsp90B1, an endoplasmic reticulum–localized subtype of Hsp90, interacts with multiple mitogenic and prosurvival factors to promote cancer development and metastasis." (PMID 33579708, 2021). "Cancer signaling pathways (hsa05200) showed that HSP90B1 promotes cell proliferation and evades apoptosis by activating of androgen receptor (AR) and PSA." (PMID 32537125, 2020). "In this pathway, HSP90B1 promotes the proliferation of cancer cells and their resistance to apoptosis by activating of PSA." (PMID 32537125, 2020). "For example, HSP90B1, an HSP90 member, is associated with proliferation, metastasis, and angiogenesis across multiple cancers." (PMID 33225964, 2020). "HSP90B1 is demonstrated to be involved in the growth of cancerous cells, and HSP90B1 inhibitors can reverse cancer cell growth and increase survival." (PMID 27846214, 2016). "It has been reported that high expression levels of HSP90B1, also known as gp96 and Grp94, are correlated with cancer cell survival and epithelial ovarian cancer." (PMID 27046189, 2016). "Recent studies have indicated that HSP90B1 inhibitor is more effective than hormone and growth receptor inhibitors for anti-cancer growth." (PMID 27046189, 2016). "In particular, four genes within pathways in cancer were differentially expressed in the same direction under all the three conditions, including HSP90B1, ARAF, and RUNX1, being downregulated, and CDK4, being upregulated under these three manipulations." (PMID 25007077, 2014). "Of the 990 cases 928 (94%), 967 (98%) and 930 (94%) were interpretable for DCN staining in stroma, DCN staining in the carcinoma and HSP90B1 staining in the carcinoma, respectively." (PMID 22363530, 2012). "High expression of DCN in stroma, carcinoma and HSP90B1 staining in carcinoma was seen in 76%, 34% and 84% of cases, respectively." (PMID 22363530, 2012).